IL33 (interleukin 33)
Diseases named in the same sentence as IL33 in open-access papers (continued):
Sharing a sentence is not in itself a finding about the gene and the disease.
Ascites (1 paper, 2023). Accumulation of fluid in the peritoneal cavity (between the layers of the peritoneum that lines the abdomen). "The combination of inflammatory markers and clinical variables favoured five inflammatory markers (TWEAK, CCL4, HGF, TRANCE and IL-33) and one clinical variable (ascites) with an AUROC of 0.73 and 95% CI [0.57;0.88]." (PMID 37973887, 2023).
Atrophy (1 paper, 2024). Any weakening or degeneration, especially through lack of use. "Most importantly, we found that IL-33 could alleviate disuse muscle atrophy in aged mice, suggesting a potential therapeutic application of this signaling pathway for the treatment of disuse muscle atrophy in the elderly, a condition for which no established medical intervention currently exists." (PMID 38561845, 2024).
autoimmune disorder of the nervous system (1 paper, 2018). A disorder characterized by the degeneration of the nervous system due to autoimmunity. "Interleukin-33 (IL-33) orchestrates inflammatory responses in a wide range of inflammatory and autoimmune disorders of the nervous system." (PMID 29329586, 2018).
autonomic dysfunction (1 paper, 2023). "Aim of the study is to evaluate the serum level of IL-33 and sST2 and to assess the relationship between serum level of IL-33 or sST2 and diastolic dysfunction, autonomic dysfunction and right ventricle impairment in SSc patients." (PMID 35877052, 2023).
bacterial meningitis (1 paper, 2015). Inflammation of the membranes surrounding the brain and spinal cord due to a bacterial infection. "Most interestingly, these factors may positively (e.g., IL33 and IL18rap) and negatively contribute to regulation of NF-κB, which is a hallmark feature of bacterial meningitis." (PMID 25993608, 2015). "Most interestingly, these factors may positively (e.g., IL33 and IL18rap) and negatively (Tnfaip3, CISH and Zfp36) contribute to regulation of NF-κB, which is a hallmark feature of bacterial meningitis." (PMID 25993608, 2015).
bacterial pneumonia (1 paper, 2021). Acute infection of the lung parenchyma caused by bacteria (e.g., Streptococcus pneumoniae, Haemophilus influenzae, Chlamydia pneumoniae, Mycoplasma pneumoniae, and Legionella pneumophila). "In IAV-infected mice, attenuation of bacteria-induced IL-33 was shown to predispose to secondary bacterial pneumonia by reducing neutrophil function." (PMID 34960788, 2021).
basal cell carcinoma (1 paper, 2021). A carcinoma involving the basal cells. "Thus, we investigated the effects of the major active form of vitamin D (1,25(OH)2D3) on the expression of IL-33 at mRNA and protein levels in skin-derived cell lines: keratinocytes, melanocytes, fibroblasts, and basal cell carcinoma cells." (PMID 34884710, 2021). "In the A431 basal cell carcinoma cell line, the expression of IL-33 and ST2 was significantly stimulated by 1,25(OH)2D3 at all time points with the greatest effect after 4 h for IL-33 and after 8h for ST2." (PMID 34884710, 2021). "Potential effects of 1,25(OH)2D3 and its receptor (VDR) on the expression of IL-33 and ST2 were tested in cultured keratinocytes, melanocytes, fibroblasts, and basal cell carcinoma cells." (PMID 34884710, 2021).
behavioral disorders (1 paper, 2018). "The findings of IL-33 involvement in exciting sensory neurons, axonal myelination and synapse homeostasis also imply that dysregulated IL-33/ST2 signaling may lead to CNS neurological and behavioral disorders." (PMID 30515150, 2018).
benign prostatic hyperplasia (1 paper, 2025). A non-cancerous nodular enlargement of the prostate gland. "In addition to studies conducted in Chinese populations, research from a Canadian cohort has demonstrated that IL-33 expression is significantly reduced in metastatic prostate cancer (PCa) compared to primary PCa or benign prostatic hyperplasia (BPH)." (PMID 40607441, 2025). "explore IL-33 expression in PCa using bioinformatics analyses (TCGA, TIMER, HPA databases), followed by validation in clinical samples (PCa, benign prostatic hyperplasia [BPH], and non-cancerous tissues)." (PMID 40607441, 2025).
bladder tumor (1 paper, 2023). "We first confirmed the high expression of ST2 by bladder ILC2s compared to ILC1s and 3, which remained stable along the bladder tumor growth, consistent with previous observations and suggesting that bladder ILC2s may be responsive to IL-33." (PMID 38283350, 2023). "Targeting ILC2s by blocking IL-4/IL-13 signaling pathways, IL-5, or IL-33 receptor, or using IL-33-deficient or ILC2-deficient mice, did not affect mice survival following bladder tumor implantation." (PMID 38283350, 2023). "However, the absence of ILC2s in these mice did not affect the mice survival following bladder tumor challenge, in line with the results obtained when blocking IL-4/IL-13 or IL-5 signaling pathways, or IL-33/ST2 axis." (PMID 38283350, 2023).
Blindness (1 paper, 2022). Blindness is the condition of lacking visual perception defined as a profound reduction in visual perception. "In summary, our observations identify IL-33 as a potential therapeutic target for pathological retinal angiogenesis, which is a leading cause of blindness in various retinopathies such as ROP, DR, and AMD." (PMID 35589941, 2022).
bone fracture (1 paper, 2021). "Bone fracture also promotes the release of damage-associated molecular patterns (DAMPS), such as HMGB-1 or heat shock protein 70 (HSP-70), and alarmin cytokines such as interleukin-33 (IL-33)." (PMID 34956079, 2021).
brain edema (1 paper, 2018). Increased intracellular or extracellular fluid in brain tissue. "Together, these data demonstrate that IL-33/ST2 signaling mitigates TBI-induced brain edema, motor function outcome, spatial learning and memory deficits, at least in part, by a mechanism involving suppressing autophagy, ER stress, apoptosis and neuroinflammation." (PMID 29922130, 2018). "We observed that administration of IL-33 with dosages of 50 ng/μl, 80 ng/μl or 100 ng/μl could significantly alleviate TBI-induced brain edema, and the optimum concentration of IL-33 for the best therapeutic effect is 50 ng/μl." (PMID 29922130, 2018).
bronchoconstriction (1 paper, 2021). Bronchoconstriction involves narrowing of air passage lumina, typically due to bronchial smooth muscle contraction, and leads to decreased air flow. "IL33 was reported to be a central activator of dendritic cells during HDM allergic sensitization and to exacerbate allergic bronchoconstriction." (PMID 34440118, 2021).
calcific aortic valve disease (1 paper, 2023). "Immunohistochemical analysis showed that sST2 and IL-33 were mainly colocalized with CD68 positive macrophages in stenotic valves, suggesting that sST2 may participate in the pathophysiology of calcific aortic valve disease via the inhibition of IL-33 in macrophages." (PMID 37371771, 2023).
carbon monoxide poisoning (1 paper, 2022). A poisoning that is caused by exposure to carbon monoxide. "WIN 55,212-2 (an agonist for cannabinoid receptors) both promotes IL-33 production and inhibits microglial activation induced by carbon monoxide poisoning." (PMID 36439205, 2022). "Furthermore, IL-33/ST2 signaling and CD206-positive microglia are simultaneously induced by cannabinoids in carbon monoxide poisoning." (PMID 36439205, 2022).
cardiac arrest (1 paper, 2020). Cessation of breathing and/or cardiac function. "In this single-center, case-control study, we measured the plasma levels of IL-17, IL-22, IL-23 and IL-33 in 21 cardiac arrest patients with ROSC at three time-points (baseline [within 1 h post ROSC], 2 days post ROSC and 7 days post ROSC)." (PMID 32293300, 2020).
carotid atherosclerosis (1 paper, 2024). A thickening and loss of elasticity of the walls of carotid arteries that occur with formation of atherosclerotic plaques. "Also, increased level of IL-33 was associated with thrombotic complications and progression of carotid atherosclerosis in patients with rheumatoid arthritis." (PMID 38519881, 2024).
Chagas disease (1 paper, 2025). A parasitic infection caused by Trypanosoma cruzi. "In the context of murine acute T. cruzi infection, a model for Chagas’ disease with a profound compromise of various target tissues, including SM, our results reveal a novel scenario marked by a diminished trTreg response and reduced plasmatic IL-33 concentration despite extensive tissue damage." (PMID 39883714, 2025). "Our work highlights the balance between microbicidal and regenerative responses driven by trTregs and the IL-33/ST2 axis, which is still not well understood in infections and may be particularly relevant to the progression of acute Chagas’ Disease." (PMID 39883714, 2025).
chlamydial infection (1 paper, 2021). "IL-18 and IL-33 participate in immunologic injury induced by chlamydial infection, although the precise mechanisms in removing chlamydial are still unknown." (PMID 34093528, 2021). "Because Th2 cytokines can suppress Th1 responses and inhibit IFN-γ production, it is not likely that IL-33 functions in blocking chlamydial infection." (PMID 34093528, 2021).
cholangitis (1 paper, 2021). An acute or chronic inflammatory process affecting the biliary tract. "Therefore, we investigated whether this pathway is involved in progressive fibrosis after cholangitis by analyzing the expression of IL33, IL13, TGFB1, and COL1A1." (PMID 34858903, 2021).
cholestasis (1 paper, 2019). Impairment of the bile flow caused by obstruction within the liver, or outside the liver in the bile duct system. "In conclusion, our study showed that compared to cholestasis controls, IL-33 and ST2 receptor expressions are significantly increased in BA livers; their interaction can induce the overexpression of downstream cytokines TGF-β1 and IL-13." (PMID 31632941, 2019).
clonorchiasis (1 paper, 2022). Infection of the biliary passages with clonorchis sinensis, also called Opisthorchis sinensis. "Our previous study showed that the expression of interleukin (IL)-33 is increased in both humans and mice infected by C. sinensis, suggesting that IL-33 is potentially involved in the pathogenesis of clonorchiasis." (PMID 36271450, 2022). "In our present study, we investigated the role and mechanisms of IL-33 in the pathogenesis of clonorchiasis using IL-33 wild-type and IL-33 germ knockout mice with BALB/c background mice." (PMID 36271450, 2022).
CNS demyelination (1 paper, 2016). A loss of myelin from nerve fibers in the central nervous system. "Poly-IC a known TLR3 agonist and IL-33, a cytokine which is induced by poly-IC are known to influence recovery and promote repair in experimental models of CNS demyelination." (PMID 27022724, 2016).
colon adenocarcinoma (1 paper, 2019). "Initially, IL-33 transcript levels from a previous study (extracted from an analysis of mRNA microarray) correlated directly with the ability of conditioned media from colorectal CAFs to induce the migration of tumor lines of colon adenocarcinoma." (PMID 31281317, 2019).
colonic disease (1 paper, 2021). "The role of IL-33 in colonic disease is controversial, as some studies suggest it is pathogenic while others have found it is associated with improved outcomes in colitis." (PMID 33547321, 2021).
colorectal tumors (1 paper, 2022). "Concomitantly, the transcript levels of Il33 and Rab27a, both important regulators of mast cells, were reduced and increased, respectively, in the colorectal tumors of Nfe2l3−/− mice." (PMID 35091681, 2022).
congenital toxoplasmosis (1 paper, 2024). Toxoplasma infection that is present from birth. "However, IL-33 has not been associated with congenital toxoplasmosis." (PMID 39065188, 2024).
Corneal opacity (1 paper, 2026). A reduction of corneal clarity. "In vivo, prophylactic adoptive transfer of IL-33-treated BMDMs significantly reduced corneal opacity, epithelial injury, tear viral titers, and virogene expression." (PMID 41754825, 2026).
cutaneous lupus erythematosus (1 paper, 2022). An autoimmune disorder that manifests as different lupus-specific skin disorders; it can occur with systemic lupus erythematosus, or as a singular disease. "However, whether IL-33/ST2 interferes with the nosogenesis of cutaneous lupus erythematosus (CLE) has not been reported so far." (PMID 35909659, 2022).
cutaneous squamous cell carcinoma (1 paper, 2025). "We show that the expression of IL-33 differentiates malignant from normal and benign human tissues and that in mouse models of cutaneous squamous cell carcinoma the IL-33/ST2 axis protects against carcinogenesis." (PMID 40517383, 2025).
demyelination (1 paper, 2018). "In animal models of CNS demyelination, IL-33 was expressed intracellularly in regions undergoing remyelination and a protective effect of IL-33 has been described in animals following experimental injury to the CNS." (PMID 30562364, 2018).
dilation (1 paper, 2023). "Early atrial dilation in AF patients can lead to physiological stretching of the atrium, causes myofibroblasts to release IL-33, which binds ST2l to myocardial cell membranes and promotes cell integrity and survival." (PMID 38274310, 2023).
Duchenne muscular dystrophy (1 paper, 2020). Duchenne muscular dystrophy (DMD) is a neuromuscular disease characterized by rapidly progressive muscle weakness and wasting due to degeneration of skeletal, smooth and cardiac muscle. "More interestingly, the IL-33/ST2 system emerged as a novel fibroblast–cardiomyocyte communication system that regulates the accumulation of anti-inflammatory T regulatory lymphocytes (Tregs) and was proposed as a biomarker for cardiomyopathy in Duchenne muscular dystrophy (DMD)." (PMID 32508664, 2020).
endometritis (1 paper, 2016). An acute or chronic, usually bacterial infectious process affecting the endometrium. "In addition, we were unable to illustrate the correlation between IL-31/IL-33 and endometritis." (PMID 27340318, 2016).
enterocolitis (1 paper, 2014). An inflammatory process affecting the small intestine and colon. "IL-33 treatment accelerated enterocolitis in the IL-10−/− mice, but similarly treated WT C57BL/6 mice were essentially protected from the IL-33-mediated mucosal inflammatory disease." (PMID 24491821, 2014).
enteropathy (1 paper, 2020). "According to these findings and considering previous works on an experimental model of enteropathy developed in wild type mice, we aimed to study whether an acute inflammatory stimulus, intragastric p31-43 and poly I:C treatments, was able to upregulate IL-33 expression in vivo." (PMID 33133101, 2020).
eosinophilic pneumonia (1 paper, 2017). An inflammatory lung disorder characterized by an increased number of eosinophils in the lungs. "Therefore, we wanted to evaluate the effect of steroid on the lung tissue-localized memory-type ST2+CD4+ T cells using our eosinophilic pneumonia model induced by intratracheal administration of IL-33." (PMID 28754914, 2017). "Thus, our results highlighted the fact that memory-type ST2+CD4+ T cells are involved in the pathogenesis of steroid-resistant eosinophilic pneumonia induced by IL-33." (PMID 28754914, 2017). "Thus, the process of IL-33-induced activation of memory-type ST2+CD4+ T cells may be a potential therapeutic target for steroid-resistant recurrent eosinophilic lung inflammation, including eosinophilic pneumonia." (PMID 28754914, 2017).
familial cancers (1 paper, 2014). "Whether and how IL-33 expression is linked auto-immune disease and familial cancers needs to be clarified." (PMID 24778632, 2014).
fascioliasis (1 paper, 2022). A parasitic infection that is caused by liver flukes, usually Fasciola hepatica, of sheep, goats, and cattle. "The infiltration of unique MC types in fascioliasis cattle is thought to indicate MC activation through not IgE but epithelial cell cytokines IL-33 and so on." (PMID 36605763, 2022).
fibromyalgia (1 paper, 2026). A chronic disorder of unknown etiology characterized by pain, stiffness, and tenderness in the muscles of neck, shoulders, back, hips, arms, and legs. "Altogether, our study identified the BDNF/IL-33 regulatory pathway as a molecular correlate of fibromyalgia, and the use of US-exposed young C57BL/6 mice as a potential model that recapitulates this syndrome." (PMID 42123637, 2026).
Genital ulcers (1 paper, 2021). "The allele frequency of IL33 SNP rs2210463 (P = 0.006, Pc = 0.048) was significantly different between patients with and without genital ulcers." (PMID 33859633, 2021).
genital warts (1 paper, 2025). "Low levels of IL-33 indicate a deficient immune response, which allows genital warts to develop and favors recurrences." (PMID 40142865, 2025). "Low serum levels of IL-21 and IL-33 can increase the risk of acquiring HPV infection and developing genital warts." (PMID 40142865, 2025). "Serum IL-33 levels were lower in patients with genital warts compared to the control group (p < 0.01)." (PMID 40142865, 2025).
gingival enlargement (1 paper, 2024). "Given IL-33’s unexplored role in amlodipine-induced gingival enlargement and its known involvement in fibrosis and inflammatory processes, it was important to examine its expression in these cases." (PMID 39204180, 2024). "The RT-PCR analysis of gingival tissue samples showed that interleukin-33 (IL-33) expression levels were significantly lower in patients taking amlodipine who developed gingival enlargement compared to those not taking amlodipine but who developed gingival enlargement." (PMID 39204180, 2024).
H. pylori (1 paper, 2018). "The levels of IL-33 mRNA and protein were significantly upregulated with WT H. pylori-strain infection compared with either no infection or infection with a ΔcagA-strain." (PMID 29691371, 2018).
Hantavirus infections (1 paper, 2015). "The utilisation of sST2 to selectively reduce IL-33/ST2, with a consequent decrease in the inflammatory response in endothelial cells, may be exploited as a therapeutic target for Hantavirus infections." (PMID 25658420, 2015).
hematoma (1 paper, 2021). A hematoma is a collection of blood from a vascular structure into an extravascular space. "Compared with the ICH group with poor prognosis, the ICH group with good prognosis had lower baseline NHISS scores (p = 0.039) and hematoma volume (p = 0.025) and higher GCS scores (p < 0.001) and serum IL-33 levels (p < 0.001)." (PMID 33854693, 2021). "The results of linear analysis further showed that the level of serum IL-33 is related to NHISS score, GCS score, and hematoma volume, and the latter is a traditional indicator for evaluating the prognosis of ICH." (PMID 33854693, 2021). "However, serum IL-33 levels in ICH patients are significantly negatively correlated with NHISS scores (r = −0.224, p = 0.033) and hematoma volume (r = −0.253, p = 0.046) and positively correlated with GCS scores (r = 0.296, p = 0.020)." (PMID 33854693, 2021).
Henoch-Schonlein purpura (1 paper, 2015). "IL-33 levels were increased in patients with disease associated with chronic inflammation such as ankylosing spondylitis, rheumatoid arthritis, Henoch-Schonlein purpura, or multiple sclerosis." (PMID 25802482, 2015). "Interestingly, the situation in an immune-complex vasculitis, Henoch-Schonlein purpura (HSP), was just the opposite; the authors described elevated IL-33 levels in acute HSP that decreased in remission." (PMID 25802482, 2015).
Hepatosplenomegaly (1 paper, 2023). Simultaneous enlargement of the liver and spleen. "IL-33 and St2 knockout mice showed similar levels of hepatosplenomegaly, peripheral blood count, and cytokine storm when compared with wild-type (WT) mice after induction of MAS." (PMID 37842289, 2023). "However, IL-33−/− or St2−/−mice did not improve hypercytokinemia, hepatosplenomegaly, or cytopenia in the CpG-induced MAS model." (PMID 37842289, 2023).
herpes infection (1 paper, 2025). "In the case of patients with warts, IL-33 expression was very low compared to those with herpes infection, in which an increased expression was observed." (PMID 40142865, 2025).